KLF4 (KLF transcription factor 4)
Diseases named in the same sentence as KLF4 in open-access papers (continued):
Sharing a sentence is not in itself a finding about the gene and the disease.
melanoma (52 papers, 2011 to 2026). A malignant, usually aggressive tumor composed of atypical, neoplastic melanocytes. "Genetic loss of KLF4 or AXL depletion reduced melanoma cell migration and invasion, suggesting a key role of KLF4 in the regulation of invasiveness." (PMID 41916083, 2026). "A recent study linked increased ER stress to the induction of KLF4 expression in melanoma cells, as an adaptive mechanism inhibiting UPR-induced apoptosis and promoting metastasis." (PMID 38807192, 2024). "Ectopic WT-Bmal1 and dHLH-Bmal1 increased genes associated with mesenchymal melanoma state, such as Sox9, Fn1, Col1a1, Prrx2, Klf4, Snai2, Twist2, Lmo1 and Axl31." (PMID 38245503, 2024). "The deficiency of KLF4 decreased lung metastatic abilities of melanoma cells, which was reversed by NUCB2 overexpression." (PMID 30055641, 2018). "Elevated KLF4 was found in human melanoma tissues, which was associated with NUCB2 expression." (PMID 30055641, 2018). "Elevated KLF4 was found in human melanoma tissues, which was associated with NUCB2 upregulation." (PMID 30055641, 2018). "Loss of function experiments revealed that KLF4 is required for melanoma cell maintenance." (PMID 28412746, 2017). "Specifically, in melanoma, miR‐150‐3p downregulates KLF4 expression, thereby preventing KLF4 from binding to the promoter region of NCK2 and suppressing its transcription, ultimately leading to inhibition of tumor cell growth." (PMID 41532367, 2026). "KLF4 directly regulates miR-182 cluster expression in human embryonic stem cells (hESCs) and in melanoma tumours, in which the miR-182 cluster is highly expressed and has a pro-metastatic role." (PMID 40831570, 2025). "In melanoma, immunotherapy targeting the PD-1 receptor can upregulate KLF4 expression, thereby improving the survival rate of melanoma patients." (PMID 39995670, 2025). "In the present study, the silencing of HIF1α, SHH, and KLF4 in melanoma CSCs resulted in marked alterations in cell morphology, cytoskeletal organization, and molecular profile." (PMID 40854961, 2025). "We analyzed the differential expression levels of stemness-related genes among different subtypes and groups, revealing that KLF4 was markedly elevated in the C2 IGFBP3+ melanoma cells." (PMID 41383633, 2025). "In this study, we employed an integrated, multi-scale approach to investigate how melanoma CSCs respond to siRNA-mediated silencing of three key regulatory genes: KLF4, SHH, and HIF1α." (PMID 40854961, 2025). "For instance, KLF4 is highly expressed in a subset of human melanomas and ectopic KLF4 expression enhances melanoma cell growth by decreasing apoptosis." (PMID 35205716, 2022). "Our previous study showed that KLF4 promoted melanoma cell metastasis by transcriptionally regulating NUCB2 expression." (PMID 33935281, 2021). "Based on this, we assessed the effect of ITIH5 on the expression of NUCB2, a known target gene of KLF4, in melanoma cells." (PMID 33935281, 2021). "We found that ITIH5 overexpression significantly suppressed cell proliferation and migration in KLF4 wild-type melanoma cells." (PMID 33935281, 2021). "Positive controls showed transcript expression for OCT4 on seminoma, SOX2 on melanoma, KLF4 on sweat glands, and c-MYC on normal colon." (PMID 33816543, 2021). "In melanoma, KLF4 (spot H) plays a pro-tumorigenic and pro-proliferative role, inhibits apoptosis, and promotes metastasis in connection with ER-stress." (PMID 34591417, 2021).
melanoma (continued). "Strikingly, KLF4 was previously reported to be as the direct downstream target in the E2F1-mediated pro-tumorigenic of melanoma." (PMID 33726845, 2021). "Given that KLF4 enhanced melanoma adaptation to ER stress, we first knocked down KLF4,KLF5 and KLF8 expression using shRNAs in Mel-RM and A375 cells." (PMID 30055641, 2018). "First, KLF4 ablation dramatically reduced melanoma adaption to ER stress and inhibited cell metastasis in vitro and in vivo." (PMID 30055641, 2018). "Compared with the control cells, deficiency in NUCB2 promoted ER stress-induced apoptosis and decreased cell migration, which was consistent with the role of KLF4 in melanoma cells." (PMID 30055641, 2018). "Here, we demonstrated that KLF4 was induced by ER stress in melanoma cells, and increased KLF4 inhibited cell apoptosis and promoted cell metastasis." (PMID 30055641, 2018). "Consistently, our findings provided a series of evidence supporting the oncogenic role of KLF4 in melanoma adaptation to ER stress." (PMID 30055641, 2018). "In summary, our study indicates that KLF4 was an important regulator in melanoma adaptation to ER stress and cell metastasis." (PMID 30055641, 2018). "Whereafter, we overexpressed NUCB2 into KLF4 KO Mel-RM cells and found that the effects of KLF4 depletion on melanoma adaptation to ER stress and metastasis were reversed by NUCB2 overexpression." (PMID 30055641, 2018). "Taken together, these data suggest that KLF4 plays an important role in regulating melanoma resistance to ER stress and facilitating cell metastasis." (PMID 30055641, 2018). "Taken together, these data indicate that the effects of KLF4 on melanoma adaptation to ER stress and metastasis were dependent on NUCB2." (PMID 30055641, 2018). "Third, the expression levels of KLF4 were increased in melanoma tissues and KLF4 was induced by ER stress in a transcriptional manner." (PMID 30055641, 2018). "We also found that KLF4 induced by ER stress promoted melanoma adaptation to ER stress and cell metastasis." (PMID 30055641, 2018). "In summary, these results demonstrate that KLF4 binds to the miR-182 cluster promoter and is necessary to drive miR-182 cluster expression in melanoma cells." (PMID 28412746, 2017). "In summary, our findings reveal KLF4 as a key regulator of miR-182 cluster expression in hESCs and a main contributor to its aberrant expression in melanoma and potentially in other tumors, thereby providing potential new avenues for therapeutic intervention." (PMID 28412746, 2017). "In the present study, we demonstrated successful reprogramming of terminally differentiated melanoma TILs that express high levels of PD-1 into human iPSCs by using SeV vectors encoding OCT3/4, SOX2, KLF4, and c-MYC." (PMID 27057178, 2016). "Furthermore, the role of KLF4 in rarer malignancies like Wilms' tumor and melanoma through circRNAs and miRNAs highlights its capacity to drive tumorigenesis in specific contexts." (PMID 41532367, 2026). "Likewise, knockout of KLF4 has been shown to reduce melanoma metastasis to the lung with concomitant reduction of MDSCs by reducing the development of MDSCs from fibrocytes through the regulation of fibroblast-specific protein-1 (FSP-1)." (PMID 40552304, 2025). "Interestingly, OCT3/4, NANOG and Klf4 mRNAs were up-regulated by 680C91, suggesting a critical role of stem cell markers in regulating melanoma cell malignancies." (PMID 38794128, 2024). "Moreover, melanocytes and melanoma cells have been dedifferentiated to iPSCs by transfecting in Oct4, c-Myc, and Klf4 expression vectors." (PMID 37270599, 2023). "Moreover, IHC studies revealed that the expression of NUCB2 was positively correlated with KLF4 in melanoma tissues." (PMID 34361082, 2021). "Interestingly, KLF4 was shown to regulate transcription of NUCB2 by binding to its promoter which induced melanoma ER stress resistance, tumor growth, and cell metastasis in vitro and in vivo." (PMID 34068679, 2021).
melanoma (continued). "We therefore wanted to determine whether ITIH5 suppresses melanoma malignancy by downregulating KLF4." (PMID 33935281, 2021). "Although KLF4 acts as a oncogene in osteosarcoma, melanoma, and bladder cancer, the biological role of KLF4 in HB remains unknown." (PMID 33052880, 2020). "In addition, KLF4 promoted melanoma ER stress resistance, tumour growth and cell metastasis by regulating NCUB2 expression in vitro and in vivo." (PMID 30055641, 2018). "Additionally, an increase in KLF4 promoted melanoma ER stress resistance, tumour growth and cell metastasis by regulating NCUB2 expression in vitro and in vivo." (PMID 30055641, 2018). "By RT-real time PCR analysis, we could observe that the expression of the embryonic transcription factors SOX2 and KLF4 is significantly increased in spheroid-derived cells, when compared to A375 adherent melanoma cells." (PMID 29330434, 2018). "Here, we found that KLF4, a zinc finger-type transcription factor, was induced by ER stress, leading to the inhibition of cell apoptosis and the promotion of cell metastasis in melanoma." (PMID 30055641, 2018). "Our data revealed that the promotion of ER stress resistance via the KLF4-NUCB2 axis is essential for melanoma cell metastasis, and KLF4 may be a promising specific target for melanoma therapy." (PMID 30055641, 2018). "Recent studies indicated that KLF4 was increased in melanoma and enhanced tumour growth." (PMID 30055641, 2018). "Concurring with this hypothesis, shRNA mediated knockdown of KLF4 in melanoma cells reduced their ability to migrate in a wound-healing assay and to invade in a transwell cell invasion assay." (PMID 28412746, 2017). "However, our experimental validation determined that only KLF4 is bound to the promoter region of the miR-182 cluster in physiologic conditions (hESCs) and in a subset of melanoma cell lines." (PMID 28412746, 2017). "In fact, gene expression analyses in metastatic melanoma samples (GSE19324, n = 44) showed higher levels of KLF4 mRNA in patients with poor outcome suggesting that KLF4 could contribute to melanoma metastatic progression." (PMID 28412746, 2017). "Therefore, alantolactone combined MAPKi could dual suppress STAT3 and BRAF/MEK/ERK1/2 pathways, consequently inhibiting the expression of downstream Klf4, Oct4, Sox2 and c-Myc proteins, to enhance sensitivity of resistant melanoma to MAPKi." (PMID 38822350, 2024). "Therefore, we sought to analyze whether KLF4 could be regulating similar processes and potentially be a new therapeutic target in melanoma." (PMID 28412746, 2017). "Interestingly, miR-10b was reported to be one of the most downregulated miRNAs in melanoma, suggesting that miR-10b restoration could have a therapeutic impact in melanoma through the downregulation of KLF4." (PMID 28412746, 2017). "On the other hand, enforced expression of TAF4 promoted expression of pluripotency- associated KLF4, OCT4 and NANOG, and NC-related MSX2, PAX7, SOX10 and SNAI1, reaffirming the critical role of hTAF4-TAFH activity in the maintaining of multipotency in melanoma cells." (PMID 27499390, 2016). "Surprisingly, KLF2 and KLF4 were dispensable for the proliferative and anti-apoptotic effects of compensatory ERK5 activation in MEKi-exposed melanoma." (PMID 41916083, 2026). "Our study describes a novel ERK5/KLF4/AXL signaling axis that drives MEKi resistance and metastatic potential in NRAS-mutant melanoma and highlights this axis as a potential target to improve MAPK-directed and potentially immune therapies." (PMID 41916083, 2026). "This study demonstrates that silencing KLF4, SHH, and HIF1α in melanoma CSCs leads to coordinated changes in cytoskeletal structure, molecular composition, and cell morphology, reflecting a loss of stem-like properties." (PMID 40854961, 2025). "In this study, we aimed to investigate how silencing of the KLF4, SHH, and HIF1α genes affects the cytoskeletal structure and biochemical characteristics of melanoma CSCs." (PMID 40854961, 2025).
melanoma (continued). "The integration of molecular, spectroscopic, and imaging data provides a comprehensive perspective on how silencing of KLF4, SHH, and HIF1α affects melanoma CSCs." (PMID 40854961, 2025). "In a later work, constitutive expression of OCT4, KLF4, and SOX2 in BRAF-mutant HT-144 human melanoma cells produced metastable iPSCs with reduced tumorigenicity and therapeutic resistance against MAPK inhibitors." (PMID 38247819, 2024). "Of note, nests of stem-like melanoma cells have been identified in metastatic lesions in head and neck cancer patients and shown to express NANOG, OCT4, SOX2, KLF4, and cMYC." (PMID 37270599, 2023). "KLF4 and Nanog were reported to be downstream target in the E2F1-mediated pro-tumorigenic of melanoma and self-renewal of hepatocellular CSCs." (PMID 33726845, 2021). "Kruppel-like factor 4 (KLF4) and sex-determining region Y-box 2 (SOX2) have been reported as essential transcription factors that maintain CSC stemness and invasion activity in melanomas, in addition to many other cancer cells." (PMID 34106558, 2021). "Here we show the induction of the self-renewal and pluripotency markers Nanog, KLF4, OCT4, and SOX2 and the over-expression of the CSC markers CD133, CD243, and ALDH1A1 in melanoma cells exposed to chronic acidosis compared with control cells." (PMID 32803272, 2020). "Similar to our observations of KLF4 action in TNBC cells, KLF6 is a tumor suppressor that inhibits metastasis and the EGFR/AKT pathway in melanoma and lung adenocarcinoma." (PMID 32552913, 2020). "This transcriptome cluster was predicted to be dependent on Kruppel-like factor 4 (KLF4), which is a downstream target of the RAS/RAF/MEK/ERK signaling pathway and is required for melanoma survival through the inhibition of apoptosis." (PMID 29762513, 2018). "We found that the relative expression levels of KLF4 and NUCB2 were significantly increased in melanoma tissues, and the protein level of KLF4 was positively correlated with NUCB2 in melanoma tissues." (PMID 30055641, 2018). "Here, we report successful generation of human iPSCs from terminally differentiated melanoma TILs that express high levels of PD-1 by Sendai virus- (SeV-) mediated transduction of the four transcription factors OCT3/4, SOX2, KLF4, and c-MYC." (PMID 27057178, 2016). "Here, we describe the derivation of human iPSCs from melanoma TILs expressing high level of PD-1 by Sendai virus-mediated transduction of the four transcription factors, OCT3/4, SOX2, KLF4, and c-MYC." (PMID 27057178, 2016). "The melanoma CSC markers SOX2, KLF4, and CD271 exhibited reduced expression profiles in the A375 IGFBP5 OE cells compared to empty vector control cells." (PMID 26010068, 2015). "The ectopic overexpression of Oct-3/4 in melanoma cell lines was also effective to enhance their expression of stem cell-like markers such as CD271, MDR1, ABCG2, ABCB5, Kruppel-like factor 4 (KLF4) and Nanog and self-renewal capacity." (PMID 23301832, 2013). "In NRAS-mutant melanoma, compensatory ERK5 activation is accompanied by the induction of the Krüppel-like factors KLF2 and KLF4 but their role in MEKi resistance remains unclear." (PMID 41916083, 2026). "R545 murine melanoma cells were reprogrammed with Oct4, Klf4, and c-Myc pluripotency inducers to obtain non-tumorigenic cancer-iPSCs." (PMID 38247819, 2024). "The stemness gene Kruppel-like factor 4 (KLF4) is also upregulated by CD133 in this NF-κB pathway, in agreement with our previous results showing upregulation of other stemness genes such as Oct4 and ABCB5 in CD133(+)-enriched BAKP melanoma stem cells." (PMID 38727313, 2024). "To understand the potential molecular mechanism of the suppressive effect of ITIH5 on KLF4-mediated melanoma progression, we first evaluated the protein levels of KLF4 in melanoma cells with or without ITIH5 knockdown or overexpression." (PMID 33935281, 2021). "Unexpectedly, we found that overexpression or knockdown of ITIH5 did not change KLF4 protein levels in melanoma." (PMID 33935281, 2021).
melanoma (continued). "In addition, our data demonstrated that ITIH5 was a bona fide interacting protein of KLF4 that suppressed the transcriptional activity of KLF4 and downregulated its target gene NUCB2, leading to the suppression of melanoma." (PMID 33935281, 2021). "Moreover, we analyzed the expression levels of KLF4, NANOG, OCT3/4, and CD271, which are genes involved in stemness features and are able to induce pluripotency in melanoma." (PMID 34298765, 2021). "Moreover, we were able to show a significant correlation of genes most strongly induced in 3D alginate, with genes induced in malignant melanoma compared to primary melanocytes, including KLF2, KLF4, and EGR1." (PMID 34439267, 2021). "Quantitative real-time PCR results showed that the PTBP1 silencing led to significant downregulations of stemness genes (Klf4, Nanog, Oct4, and Sox2) compared with the controls, indicating that PTBP1 played a positive role in maintaining the stemness of melanoma stem cells." (PMID 33149126, 2020). "We found that KLF4 induced by ER stress could directly bind to the promoter of NUCB2 and promote NUCB2 expression, leading to the increase in melanoma ER stress resistance and cell metastasis." (PMID 30055641, 2018). "Among the several transcription factors predicted to bind this region, Krüppel-like factor 4 (KLF4) showed the highest trans-activation capacity, and expression correlation with miR-182 in melanoma cell lines without 7q amplification." (PMID 28412746, 2017). "Among them, KLF4 and KLF10 where those TFs that best correlate with miR-182 in melanoma cell lines." (PMID 28412746, 2017). "Chromatin Immunoprecipitation (ChIP) analysis confirmed the physical binding of KLF4 to the miR-182 cluster promoter in melanoma cell lines but not in melanocytes, in which miR-182 is not expressed." (PMID 28412746, 2017). "Moreover, a higher level of KLF4 correlates with elevated NUCB2 in human melanoma tissues, suggesting that NUCB2 may be important in the regulation of melanoma metastasis under ER stress." (PMID 34068679, 2021). "Expression of OCT4 or transmembrane delivery of OCT4 protein promotes dedifferentiation of melanoma cells to CS/IC-like cells possessing an increased tumorsphere-formation capacity, an enhanced tumorigenic capacity and increased expression levels of endogenous OCT4, NANOG and KLF4." (PMID 28768501, 2017). "More recently, Lxn has been shown to inhibit melanoma cell proliferation and down-regulate the expression of several stem cell transcription factors, such as octamer-binding transcription factor 4 (OCT4), sex determining region Y-box 2 (SOX2), Kruppel-like factor 4 (KLF4), NANOG, and MYCN." (PMID 25551472, 2014). "However, the overexpression of miR-182 was not able to rescue the effects of KLF4 silencing (data not shown), thereby suggesting that other KLF4 targets may also be relevant to KLF4 pro-survival effects in melanoma." (PMID 28412746, 2017).